PRRX1 (paired related homeobox 1)
Diseases named in the same sentence as PRRX1 in open-access papers (continued):
Sharing a sentence is not in itself a finding about the gene and the disease.
tumor (82 papers, 2014 to 2025). "PRRX1, a transcription factor located on chromosome 1q24, is abnormally expressed in various diseases and is implicated in tumor metastasis." (PMID 40860778, 2025). "We observed that the PRRX1-high tumours expressed several cancer-associated genes (e.g. MMP2/9, ZEB2, VIM)." (PMID 34496784, 2021). "The present study demonstrates that deficiency of Prrx1 expression is critical for the role of the SDF-1/CXCR4 axis during tumour metastasis." (PMID 31752959, 2019). "In xenograft tumours and clinical samples, loss of Prrx1 was negatively correlated with increased expression of CXCR4 in lung metastatic sites compared with that in the primary foci." (PMID 31752959, 2019). "This indicated that PRRX1 played a key role in regulating the biological behavior of tumor cells, and the loss of its function could lead to a decrease in the proliferative and invasive capabilities of tumor cells." (PMID 39896800, 2024). "Functional annotation of the PRRX1 signature genes revealed a strong association with immune-related genes and processes, displaying both antitumor (Th1) and tumor-tolerant (Th2) responses, which was consistent with the predicted enrichment of immune cells in the PRRX1high subgroup." (PMID 36968142, 2023). "In addition, it interacts with the PRRX1 gene, associated with tumor malignancy." (PMID 40425856, 2025). "The tumor cell fraction (Mycn+) was decreased from 96.45% (control) to 51.01% (indisulam), while the mesenchyme-like cell fraction (Prrx1+) was increased from 0.80% to 4.23%, and the Schwann-like cell fraction was increased from 0.29% to 4.26%." (PMID 40962798, 2025). "To validate our findings, we employed Kaplan-Meier survival curves and ROC curves to analyze the key genes associated with C2 tumor cell subtypes, including the top five transcription factors (IGF2, PRRX1, MAFB, LBX2, GATA2, MAFG)." (PMID 39896800, 2024). "In summary, our results suggest that the knockdown of PRRX1 inhibits the activity, migration, invasion, and proliferation of tumor cells, thereby hindering tumor growth." (PMID 39896800, 2024). "We observed that the expression of PRRX1 in the C2 subtype was significantly higher compared to other tumor cell subtypes." (PMID 39896800, 2024). "BMX transcript levels strongly increased upon PRRX1 expression in this model, confirming a link between tumor cell phenotypes and BMX expression in NB." (PMID 39133652, 2024). "Studies showed that after knocking down the expression of PRRX1 using RNA interference technology, the proliferative and migratory abilities of tumor cells were significantly reduced." (PMID 39896800, 2024). "Inhibition of the Paired Related Homeobox 1 (Prrx1) gene is also important for tumor cells to obtain stem cell characteristics and metastatic colonization." (PMID 36770654, 2023). "Then the results of immunological characteristics demonstrated that higher expression of PRRX1 was accompanied by higher expression of immune checkpoint genes, lower tumor mutation burden (TMB), and greater tumor cell infiltration into the TME." (PMID 35281030, 2022). "When the tumor volume reached 30 mm3, Prrx1 deletion in fibroblasts was initiated by administering sgRNA against Prrx1 (sgPrrx1) to the FS-CAS9 mice." (PMID 35589735, 2022). "The clinical implications of CAF-specific PRRX1 expression prompted the investigation into the role of Prrx1 in the tumor-promoting ability of CAFs in vivo." (PMID 35589735, 2022). "PRRX1, a strong mesenchymal inducer, is activated to promote the acquisition and maintenance of robust mesenchymal features for tumor cells to migrate to their destination." (PMID 35267510, 2022). "Tumor cells were cografted with fibroblasts into immunodeficient mice, and the effect of Prrx1 expression on fibroblast-driven tumor progression was evaluated." (PMID 35589735, 2022).
tumor (continued). "Several studies suggested the role of PRRX1 in the regulation of tumor progression and metastasis through the regulation of the EMT, and acting as a ETM-TF that regulates stemness activity and EMT plasticity in TME." (PMID 35281030, 2022). "All these evidences pointed to the promising potential of PRRX1 as a marker of tumor immune infiltration." (PMID 36483329, 2022). "In vivo bioluminescent imaging of orthotopic tumors revealed that silencing PRRX1 in TGS‐01 cells accelerated tumor growth and consistently shortened the survival of the mice." (PMID 34214250, 2022). "An in vivo model of tumor recurrence was established using Col1a2;rtTATetO7-Prrx1Luc mice, and the effect of fibroblast-specific Prrx1 expression on tumor recurrence was evaluated." (PMID 35589735, 2022). "Although it cannot be concluded that α-SMA-positive cells are simply tumor-restraining CAFs (see the Section 1), targeting PRRX1 can be a promising strategy for reprograming tumor-promoting subtype of CAFs to tumor-restraining subtype of CAFs." (PMID 33572223, 2021). "We examined the expression pattern of PRRX1 in nine microarray datasets of human HCC tumour samples (n > 1100) and analyzed its function in HCC cell lines." (PMID 34496784, 2021). "In vivo studies have shown that high expression levels of PRRX1, a member of the paired family of homeobox proteins that functions as a transcription co-activator, promoted cellular plasticity and tumour dormancy of HNSCC cells." (PMID 34944837, 2021). "In this study, we combined bioinformatics analysis of a large cohort averaging over 1000 HCC tumour samples to resolve the expression pattern of PRRX1 in HCC." (PMID 34496784, 2021). "Paired-related homeobox 1 (PRRX1) is a transcriptional co-activator that promotes EMT process during tumor progressions." (PMID 37303943, 2021). "Taken together, we identify ZEB1 and ZEB2 as EMT genes correlated with PRRX1 and assumingly acting with it to influence tumour characteristics." (PMID 34496784, 2021). "It was shown that overexpressed PRRX1 was closely correlated with downregulation of miR-642b-3p and led to increased tumour cell invasiveness and migration." (PMID 34944837, 2021). "The survival time was analyzed with a Kaplan–Meier curve and the results revealed that Prrx1 knockdown significantly prolonged survival time of tumor-bearing nude mice." (PMID 34131109, 2021). "Consistent with this view, a tumour suppressor function seems incompatible with our observation of elevated PRRX1 in HCC cohorts." (PMID 34496784, 2021). "These two isoforms of PRRX1 have therefore a reciprocal relationship in regulating cellular plasticity and regulate tumor progression at different stages." (PMID 33572223, 2021). "Collectively, our findings showed that the PRRX1/PPARG2/FFAs signalling in SACC was important for accelerating tumour metastasis through the induction of EMT and the metabolic reprogramming of FFAs." (PMID 31657086, 2020). "This is the first study, to our knowledge, to investigate the effect of PRRX1 on tumour‐induced FFAs and we found that overexpressed PRRX1 increased FFAs levels and promoted the invasion and migration of SACC cells." (PMID 31657086, 2020). "We observed the same gradient for FFAs with higher levels at the tumour edge, where cancer cells displayed more mesenchymal features and expressed PRRX1 with a high level, compared with the centre of the tumour." (PMID 31657086, 2020). "To further explore the inhibitory role of PRRX1 in tumor growth, we generated cell lines to stably overexpress PRRX1 in SW480 (PRRX1oe SW480) and HCT-116 (PRRX1oe HCT-116) cells." (PMID 32811812, 2020). "In 2012, Ocana firstly discovered that PRRX1 promoted the EMT of tumor cells and was associated with tumor metastasis." (PMID 32811812, 2020). "(E) Safranin O staining showed that IWP2 rescued joint disruption and cartilage tumor formation in Prrx1-CreERT; Ptch1f/f mouse." (PMID 31482846, 2019).
tumor (continued). "(H) Osteogenic tumor-like nodules counts in control and Prrx1-CreERT; Ptch1f/f mice treated with either vehicle or IWP2." (PMID 31482846, 2019). "(E) Quantitative PCR analysis of Hh target genes of tumor tissues isolated from Prrx1-CreERT; Ptch1f/f mice." (PMID 31482846, 2019). "An IHC assay to assess metastatic HCC also showed expression of Prrx1 that was significantly lower in the lung metastatic foci than in the paired primary tumour." (PMID 31752959, 2019). "Additionally, tumours derived from shPRRX1 cells showed lower expression of PRRX1 and Ki-67 than those derived from control cells." (PMID 38448751, 2024). "By modulating the regulatory modules involving PRRX1, new drugs could be developed to inhibit its activity, thereby blocking the proliferation and metastasis of tumor cells and improving patient treatment outcomes." (PMID 39896800, 2024). "Corroborating our results, several groups have reported that high expression of PRRX1 not only promotes tumour cell malignancy, but also plays an important role in cancer associated fibroblasts (CAFs) in promoting tumorigenesis, metastasis and cancer recurrence." (PMID 38448751, 2024). "A limitation of the present study was that the association between increased PRRX1 expression and tumour malignancy progression has not been sufficiently proven to be applicable to other malignancies, so further experiments are needed." (PMID 38448751, 2024). "Recently, Prrx1 was reported to have oncogenic or tumour-suppressive functions in several tumours." (PMID 38448751, 2024). "In addition, PRRX1 impacts the division and metastasis of various tumor cells via Wnt/β-catenin and Notch pathways, and maintains the characteristics of tumor stem cells to promote EMT." (PMID 36843929, 2023). "Overexpression of EMT transcription factors such as Prrx1 could significantly increase tumor invasiveness and subsequently promote distant metastasis." (PMID 37789961, 2023). "Furthermore, 15 seed genes were further characterized to identify initially the potential of IL1RN and PRRX1 as markers of tumor immune infiltration in CRC tissues." (PMID 36483329, 2022). "The contribution of Prrx1+ CAF to tumor behavior has been well documented in various studies." (PMID 35589735, 2022). "However, Prrx1-deleted MMTV-CAFs failed to completely enhance the growth of cografted tumors, indicating that Prrx1 is essential for the tumor-promoting ability of MMTV-CAFs." (PMID 35589735, 2022). "Moreover, studies of PRRX1 in alternative tumor contexts also focus mostly on its induction of the EMT process in tumor cells, which leads to implications of proliferation, migration, and invasion of tumor cells." (PMID 36483329, 2022). "However, there exists little report on the potential of PRRX1 to interact with tumor immune infiltration and thus affect patient prognosis." (PMID 36483329, 2022). "In addition, as the tumor pathology progressed, the expression of PRRX1 in CRC tissues gradually increased." (PMID 36483329, 2022). "LLC1-Luc-GFP cancer cells were transplanted into Col1a2;rtTATetO7-Prrx1Luc mice, and tumor growth and lung and liver metastases were found to be significantly enhanced in the fibroblast-specific Prrx1-expressing group [Dox (+)] compared with Dox (−) control group." (PMID 35589735, 2022). "This contradiction might be attributed to the diverse functions of PRRX1 isoforms, namely PRRX1b that activates EMT, whereas PRRX1a that activates MET, and this isoform switching underlies tumor invasion and metastatic colonization in pancreatic cancer." (PMID 35601657, 2022). "Additionally, a specific mouse model of postsurgical tumor recurrence was generated using fibroblast-specific Prrx1-inducible mice." (PMID 35589735, 2022).
tumor (continued). "Thus, we stratified TCGA HCC dataset into high versus low PRRX1-expressing tumour samples, and analyzed the differential gene expression." (PMID 34496784, 2021). "Our results suggest that PRRX1 controls metabolism, has a tumour suppressive role, and may function in cooperation with ZEB1/2." (PMID 34496784, 2021). "Thus, based on the pattern of association with clinical parameters observed by others and us, PRRX1 can be considered as a tumour suppressor in HCC, at least in the advanced stages of the disease." (PMID 34496784, 2021). "Our experimental data with cell lines support a tumour suppressor function for PRRX1 in HCC." (PMID 34496784, 2021). "On the contrary, PRRX1 has also been shown to exert tumour suppressor functions." (PMID 34496784, 2021). "The exact role of PRRX1 in controlling the predicted cancer processes needs empirical validation, especially given that the knockdown of PRRX1 induced pro-cancer activities whereas its high expression in tumours had marginal clinicopathological correlation." (PMID 34496784, 2021). "Consistent with its expression pattern, Prrx1 has dual roles in tumor occurrence and progression." (PMID 34131109, 2021). "We therefore hypothesize that PRRX1 is important for tumour invasion and metastasis through both the induction of EMT and the metabolic reprogramming of FFAs." (PMID 31657086, 2020). "Considering the variations among different types of tumours, there may be tissue‐specific mechanisms of PRRX1 regulation in response to cancer metastasis and prognosis." (PMID 31657086, 2020). "Images showed that cells in the tumor region are Prrx1+ (red)." (PMID 31482846, 2019). "In vivo, mice bearing tumours of Prrx1 low-expressing cells had significantly shorter survival." (PMID 31752959, 2019). "Therefore, targeting PRRX1 may be a potential strategy to reprogram CAFs from a tumor-promoting subtype to a tumor-suppressing subtype." (PMID 36010986, 2022). "To better understand Prrx1 role in vivo, we generated genetically engineered mouse models that satisfied the following conditions: the mice should be immunocompetent, and Prrx1 expression could be turned on or off in indigenous fibroblasts within tumor-bearing mice." (PMID 35589735, 2022). "Moreover, we also proved that PRRX1 suppressed the growth of tumor in vivo." (PMID 32811812, 2020). "Notably, we also found that PRRX1 repressed CRC tumor growth in nude mice." (PMID 32811812, 2020). "We created a Ptpn11 LOH mouse model in PRRX1-expressing cells, and found that SHP2 deficiency in PRRX1+ OCPs was involved in the pathogenesis of cartilage lesions, indicating that SHP2 functions as a tumor suppressor in cartilage and is required in OCPs for cartilage development and homeostasis." (PMID 29644115, 2018). "In contrast, in a recent report depicting six master regulators (AEBP1, HOPX, PRRX1, SNAI2, ZEB1, ZEB2) of the TCGA “mesenchymal” subtype, they employed a network-based strategy to uncover the molecular mechanism underlying the discrete mesenchymal subtype in whole tumor tissues of serous OC." (PMID 27081703, 2016). "MMP2, COL6A3, PRRX1, COL1A2, GREM1 and SNAI2 are integral to the EMT process, a key driver of metastasis that allows tumor cells to detach and invade distant tissues." (PMID 39920655, 2025). "The master transcriptional factors of MES state cells, such as c-MYC, PRRX1 and NOTCH1 were highly upregulated in the resistant tumor cells, together with the SCP marker S100B and stem cell markers KIT and SALL4." (PMID 40962798, 2025).
tumor (continued). "Therefore, PRRX1 was not only considered a potential biomarker for predicting patient outcomes and disease progression but also a potential therapeutic target that could be inhibited by targeted therapy to suppress tumor growth and metastasis." (PMID 39896800, 2024). "In summary, our research focused on the diversity of tumor cells in HGSOC at the individual cell level, further revealing the significance of PRRX1." (PMID 39896800, 2024). "Meanwhile, EDNRA, PRRX1, EMP1, AKR1B1, and SULF2 exerted an important role in cancer progression in other tumor types." (PMID 36816947, 2023). "Prrx1, as a novel EMT-inducing factor, is targeted and inhibited by miR-655 in breast cancer cells, so as to halt cell migration and invasion during tumor EMT progression." (PMID 35805066, 2022). "Previous studies have demonstrated that PRRX1, serve as a EMT-TF, is involved in the EMT process and tumor progression in several cancers, however, the role of PRRX1 in UM was not reported." (PMID 35281030, 2022). "A report from recent studies shows crucial roles of PRRX1 via isoform switching during MET, tumour invasion, and metastasis of pancreatic malignancy." (PMID 34868979, 2021). "Prrx1 is also highly expressed in PDAC stroma and was reported to mediate CAF activation, leading to increased ECM deposition, improved tumor differentiation, fewer circulating tumor cells, and reduced metastasis." (PMID 34646829, 2021). "TGF-β1 activates EMT in HNSCC through a SMAD-dependent pathway and is instrumental in the formation of tumor buds that detach from primary tumors in oral SCC (OSCC) via activation of ZEB1 and paired-related homeobox 1 protein PRRX1." (PMID 34771518, 2021). "TGF-β1 acts in cooperation with the nuclear transcription factor PRRX1 to regulate EMT, tumor cell migration and invasion, and dormancy in HNSCC." (PMID 34771518, 2021). "To evaluate the potential relationship of PRRX1 and FFAs in the tumour microenvironment, we analysed their expression in adjacent sections of SACC tissues by IHC staining for PRRX1 and GC/MS for FFAs." (PMID 31657086, 2020). "Compared with the primary tumour in the group of injecting subcutaneously PRRX1 overexpressed SACC‐83 cells, the concentration and category of FFAs in the metastatic tumour with PRRX1 overexpressed SACC‐83 cells via the tail vein were significantly increased." (PMID 31657086, 2020). "Targeting Prrx1 can, therefore, be a treatment strategy by reducing CAF plasticity by forcing myCAF differentiation and the conversion of tumor-promoting to tumor-restraining CAFs." (PMID 33333727, 2020). "A number of studies have reported EMT-inducers to reduce cell division in a variety of tumour models, in which removal of EMT-inducers such as Twist and Prrx1 promoted metastatic growth." (PMID 30194451, 2019). "The main factors that correlate with the embryonic mesenchymal state, tumor metastases and progression include HLA-G, HSP70, hypoxia, STAT3, CD44, SNAIL1, TWIST1, PRRX1, TGFb, WNT/bCAT, ID, and MMPs." (PMID 30899759, 2019). "Effectively, a cumulative effect of inflammatory and tolerogenic immune responses in the tumor microenvironment controlled by AIF1 and PRRX1 are identified to dictate tumor growth and metastasis." (PMID 26272668, 2015). "Moreover, cells undergoing EMT showed greater radioresistance in human tumor cells Taking these observations into consideration, we inferred that miR-124 could radiosensitize CRC cells by downregulating PRRX1, which is associated with EMT and cancer stem cells." (PMID 24705396, 2014). "Importantly, PRRX1 has been previously shown to be an EMT inducer in embryonic development and tumor progression." (PMID 40943659, 2025).